BTN3A3 (butyrophilin subfamily 3 member A3)
Description:
Plays a role in T-cell responses in the adaptive immune response.
Synonyms: BTF3; BTN3.3
Tractability: Small molecule: a structure with a bound ligand is known. Antibody: UniProt places it where antibodies can reach, with high confidence; its Gene Ontology location is reachable by antibodies, with high confidence; UniProt predicts a signal peptide or a membrane-spanning region; the Human Protein Atlas places it where antibodies can reach. PROTAC: ubiquitination databases record sites on it.
Gene: Protein-coding gene on chromosome 6 (26,440,452 to 26,453,422, forward strand). Ensembl gene ENSG00000111801.
Subcellular location: Cell membrane
Subcellular location (Human Protein Atlas): Nucleoplasm; Plasma membrane; Cytosol; Nuclear bodies; Vesicles
Pathways (Reactome):
Immune System: Butyrophilin (BTN) family interactions
Gene Ontology:
Molecular function: protein binding; signaling receptor binding
Biological process: T cell mediated immunity; regulation of cytokine production; T cell receptor signaling pathway
Cellular component: membrane; plasma membrane; external side of plasma membrane
Genetic constraint (gnomAD): Loss-of-function variants: 40 observed, 45.97 expected, observed/expected ratio (o/e) 0.87, 90% interval 0.68 to 1.13. The upper end of that interval is the gene's LOEUF score, 1.13, which puts it in group 4 of 6, group 1 being the genes least tolerant of losing a copy. Missense variants: 631 observed, 744.63 expected, observed/expected ratio (o/e) 0.85, 90% interval 0.79 to 0.9. Synonymous variants: 255 observed, 278.79 expected, observed/expected ratio (o/e) 0.91, 90% interval 0.82 to 1.01.
Homologues: Orthologues: chimpanzee BTN3A3 (99% identical), macaque BTN3A3 (91% identical). Paralogues in human: BTN3A1 (75% identical), BTN3A2 (52% identical), BTN1A1 (43% identical), BTN2A2 (40% identical), BTN2A1 (40% identical), BTNL9 (36% identical), ERMAP (28% identical), BTNL3 (27% identical), BTNL8 (26% identical), BTNL2 (23% identical), MOG (14% identical), CD276 (13% identical), and 3 more.
Diseases named in the same sentence as BTN3A3 in open-access papers:
BTN3A3 is named in the same sentence as 27 diseases in open-access papers, as found by Europe PMC text mining. Sharing a sentence is not in itself a finding about the gene and the disease. The quoted sentences say what the papers report.
breast carcinoma (6 papers, 2020 to 2025). "BTN3A3 has been also found to interact with LSECtin on tumor-associated macrophages and contribute to the promotion and survival of breast cancer cells." (PMID 36362212, 2022). "LSECtin is a transmembrane protein highly expressed in tumor-associated macrophages (TAMs), while BTN3A3 is the receptor of LSECtin on breast cancer cells." (PMID 34149914, 2021). "Either macrophage-specific ablation of LSECtin or silencing of BTN3A3 in breast cancer cells decreased CSC frequency and tumor growth." (PMID 37240071, 2023). "In fact, xenograft models of breast cancer expressing tumor cell surface BTN3A3 modulated the function of macrophages to promote the acquisition of a cancer stem cell (CSC)-like phenotype." (PMID 37240071, 2023). "Among them, there are many studies on tumor immunity of BTN3A1, which shows that it is essential for the activation of Vγ9Vδ2 T cells, while BTN3A3 is expected to become a potential therapeutic target for breast cancer." (PMID 34149914, 2021). "It has been confirmed that the interaction between LSECtin and BTN3A3 can promote the stem cell characteristics of breast cancer." (PMID 34149914, 2021). "In mice carrying human tumor xenografts, macrophage-specific LSECtin interference or BTN3A3 interference in breast cancer cells can slow tumor growth." (PMID 34149914, 2021). "Therefore, the interaction between BTN3A3 and LSECtin contributes to breast cancer progression by activating the JAK-STAT pathway." (PMID 36362212, 2022). "For example, studies on gastric cancer have found that the expression of BTN3A3 can help predict the sensitivity of gastric cancer patients to the chemotherapeutic drug fluorouracil, while in breast cancer, BTN3A3 can enhance the stemness of breast cancer cells through interaction with LSECtin." (PMID 36059652, 2022). "Anti-BTN3A3 mAb destruction of LSECtin-BTN3A3 axis has therapeutic effect on breast cancer." (PMID 34149914, 2021).
ovarian carcinoma (3 papers, 2021 to 2025). A malignant neoplasm originating from the surface ovarian epithelium. "Among the related studies of ovarian cancer, some results show that the single nucleotide polymorphism (SNP) of BTN3A3 is negatively correlated with the risk of ovarian cancer." (PMID 36059652, 2022). "The single nucleotide polymorphism (SNP) in BTN3A3 was negatively correlated with the risk of ovarian cancer 62, and BTN3A3 was associated with a lower risk of ovarian cancer recurrence." (PMID 34149914, 2021). "Research shows that BTN3A3 expression is significantly lower in ovarian cancer tissues compared to normal ovarian tissues." (PMID 39891297, 2025). "Studies using various ovarian cancer cell lines have demonstrated that knocking down BTN3A3 increases the proliferation, migration, and invasion capabilities of these cancer cells." (PMID 39891297, 2025). "In the clinicopathological data of HPA, we found that BTN3A3 expression was correlated with the prognosis of ovarian cancer." (PMID 36059652, 2022). "Firstly, we found that BTN3A3 can inhibit the proliferation, migration and invasion of ovarian cancer cells." (PMID 36059652, 2022). "Here, we found that BTN3A3 knockdown can promote the proliferation, migration and invasion of ovarian cancer cells, while overexpression of BTN3A3 can inhibit the proliferation, migration and invasion of ovarian cancer cells." (PMID 36059652, 2022). "This makes us very interested in the relationship between BTN3A3 and ovarian cancer, so a series of studies have been carried out." (PMID 36059652, 2022). "Clinical data show that ovarian cancer patients with high expression of BTN3A3 have a longer survival time, but the mechanism of BTN3A3 in the occurrence and progression of ovarian cancer is still unclear." (PMID 36059652, 2022). "Compared with BTN3A3 knockdown group, BTN3A3 knockdown combined with SCH772984 treatment significantly inhibited the migration ability of ovarian cancer cells." (PMID 36059652, 2022). "In order to understand the expression level of BTN3A3 in different ovarian cancer cells, Western blot were used to detect the protein level of BTN3A3 in six ovarian cancer cell lines (ES-2, 3AO, HO-8910, HO-8910PM, NIH : OVCAR-3 and SK-OV-3)." (PMID 36059652, 2022). "Clinical data show that ovarian cancer patients with high expression of BTN3A3 have a longer survival time, suggesting that BTN3A3 may play an important role in the occurrence and progression of ovarian cancer." (PMID 36059652, 2022). "Then, we selected two ovarian cancer cell lines ES-2 and SK-OV-3 with high expression of BTN3A3." (PMID 36059652, 2022). "The role of BTN3A3 in the occurrence and progression of ovarian cancer is unknown, but it is mentioned in only one article that BTN3A3’s SNP is negatively correlated with the risk of ovarian cancer." (PMID 36059652, 2022). "In order to further explore the mechanism of BTN3A3 inhibiting the progression of ovarian cancer, we constructed the BTN3A3 overexpression plasmid with 3 × Flag tag and the control plasmid with 3 × Flag, which were transfected into NIH : OVCAR-3 cells respectively." (PMID 36059652, 2022). "Our results suggest that BTN3A3 may be a prognostic marker and a potential therapeutic target for ovarian cancer." (PMID 36059652, 2022). "In addition, we also found that overexpression of BTN3A3 could reduce the protein level of FGF2 in the nucleus of ovarian cancer cell line 3AO." (PMID 36059652, 2022). "Therefore, we knocked down or overexpressed BTN3A3 in ovarian cancer cell lines to detect cell proliferation, migration and invasion ability, and used immunoprecipitation combined with mass spectrometry to explore the possible mechanism of BTN3A3 in the progression of ovarian cancer." (PMID 36059652, 2022). "BTN3A3 can bind to FGF2, regulate the protein level of FGF2, and then regulate the phosphorylation level of ERK1/2, thus affecting the proliferation, migration and invasion of ovarian cancer cells." (PMID 36059652, 2022).
ovarian carcinoma (continued). "However, the mechanism of BTN3A3 in the occurrence and progression of ovarian cancer is not known." (PMID 36059652, 2022).
schizophrenia (3 papers, 2019 to 2024). A major psychotic disorder characterized by abnormalities in the perception or expression of reality. "For tier 1 proteins, butyrophilin subfamily 3 member A2 (BTN3A2) and member A3 (BTN3A3) were previously reported as a target gene for schizophrenia, anxiety, cancer, etc.." (PMID 38898508, 2024).
colon cancer (2 papers, 2016 to 2021). "According to research, BTN3A3 is associated with intestinal inflammation and colon cancer." (PMID 34149914, 2021).
flu (2 papers, 2024 to 2025). "“Now, when we find cases of bird flu, we can basically swab sick birds, carcasses or feces and find out whether the virus can overcome the BTN3A3 gene, simply by looking at its sequence and determining if this virus is more or less likely to jump into humans." (PMID 39071164, 2024).
gastric cancer (2 papers, 2021 to 2022). A primary or metastatic malignant neoplasm involving the stomach. "Besides, high level of BTN3A3 expression was correlated with better disease-free survival (DFS) and OS of gastric cancer patients." (PMID 34109210, 2021).
sarcoidosis (2 papers, 2023 to 2025). Sarcoidosis is a multisystemic disorder of unknown cause characterized by the formation of immune granulomas in involved organs. "Among 19 protein-sarcoidosis associations, strong genetic colocalization evidence was observed for 8 pairs, including BTN3A3, ANXA11, ITPKA, BTN3A1, G3BP1, IL1RN, IL2RB, and NFKB1." (PMID 40075078, 2025). "The BTN3A2 and BTN3A3 genes in the butyrophylin family interactions pathway are known sarcoidosis candidate genes." (PMID 38390497, 2023). "Our eQTL/GWAS analysis also identified rs2393915 in EAs with complicated sarcoidosis associated to BTN3A2, BTN3A3 and BTN2A3P, MHC I-associated genes; other BTNL2 polymorphisms (rs2076530, rs206530), have been previously reported associated to sarcoidosis susceptibility." (PMID 38390497, 2023).
cervical cancer (1 paper, 2021). A primary or metastatic malignant neoplasm involving the cervix. "In patients with cervical cancer, compared with normal tissues, cervical cancer tissues showed a low level of BTN3A3 methylation, indicating that the immune system of women without cervical cancer may be activated by DNA demethylation." (PMID 34149914, 2021).
clear cell renal cell carcinoma (1 paper, 2025). "Butyrophilin subfamily 3 member A3 (BTN3A3) acts as a tumor suppressor in various cancer types including clear cell renal cell carcinoma (ccRCC)." (PMID 39891297, 2025).
glioma (1 paper, 2022). A benign or malignant brain and spinal cord tumor that arises from glial cells (astrocytes, oligodendrocytes, ependymal cells). "High BTN2/3 expression was correlated with OS among sexes (except BTN3A3 in women), WHO grade II (BTN2A2), III (BTN2A2, BTN3A1, and BTN3A2), and IDH-Mut (BTN2A2 and BTN3A2) in glioma." (PMID 36033440, 2022).
Hematuria (1 paper, 2024). The presence of blood in the urine. "Under Bonferroni correction (P < 0.05/525 = 9.5 × 10-5), an increase in CCM levels was associated with a reduced risk of colorectal malignancy, while BTN3A3 exhibited associations with multiple diseases, including hyperplasia of prostate, unspecified hematuria, inguinal hernia, and hypothyroidism." (PMID 38887235, 2024).
membranous nephropathy (1 paper, 2024). "In addition, we observed that BTN3A2, BTN3A3, and MICB decreased the risk of membranous nephropathy, but sRAGE and AIF1 increased this risk." (PMID 38898508, 2024).
mouth ulcers (1 paper, 2023). "Second, by using Bayesian colocalization, two correlated signals with common causal variants can be estimated at specific sites, and the causative proteins of oral ulcers (BTN3A3, IL12B, BPI, FAM213A, PLXNB2, and IL22RA2) were validated." (PMID 37369724, 2023). "Ultimately, we identified 6 potential risk genes (BTN3A3, IL12B, BPI, FAM213A, PLXNB2, and IL22RA2) of mouth ulcers with altered protein abundances in the blood." (PMID 37369724, 2023). "In conclusion, we found strong evidence supporting six novel blood proteins (BTN3A3, IL12B, BPI, FAM213A, PLXNB2, and IL22RA2) associated with mouth ulcers." (PMID 37369724, 2023). "However, only six genes (BTN3A3, IL12B, BPI, FAM213A, PLXNB2, and IL22RA2) assembled the criterion (PPH4 > 75%) in the analysis of mouth ulcers, indicating a shared single variant with mouth ulcers." (PMID 37369724, 2023). "Following this analysis, the researchers identified 6 key genes, namely BTN3A3, IL12B, BPI, FAM213A, PLXNB2, and IL22RA2, which were related to the onset of mouth ulcers." (PMID 37369724, 2023).
nonsmall cell lung cancer (1 paper, 2021). "However, BTN3A3 was considered as a tumor suppressor gene, which could promote cellular apoptosis of nonsmall cell lung cancer." (PMID 34109210, 2021).
viral infection (1 paper, 2020). "Other genes like BTN3A3 (ENSG00000111801), PRMT7 (ENSG00000132600) and COLCA2 (ENSG00000214290) are all proliferation associated genes, which may participate in the repair procedures after lung tissue damage caused by viral infection." (PMID 33505977, 2020).
tumor (14 papers, 2020 to 2025). "In addition, a juxtacrine signaling interaction between macrophages and tumor cells has implicated the LSECtin–BTN3A3 axis in CSC promotion leading to enhanced tumor growth." (PMID 34911937, 2021). "Specifically, elevated expression levels of BTN3A3 have been connected with better patient survival rates, while decreased expression connects with a more hostile tumor phenotype." (PMID 39891297, 2025). "The expression of several butyrophilin (BTN) and butyrophilin-like (BTNL) molecules was significantly altered by inflammation, including BTN1A1, BTN2A2, BTN3A3, and BTNL831, and associated with tumor development." (PMID 37369724, 2023). "This induction of stemness operates via a molecular pathway that is distinct from the Ephrin-dependent maintenance of stemness and the LSECtin–BTN3A3 axis supporting tumor growth, and involves macrophage-tumor cell contact-dependent Notch signaling." (PMID 34911937, 2021). "Compared with monotherapy, the combination of anti-BTN3A3 (5E08) mAb and paclitaxel significantly reduced tumor growth." (PMID 34149914, 2021). "Based on this result, either macrophage-specific ablation of LSECtin or silencing of BTN3A3 in mice bearing human tumor xenografts can block the LSECtin-BTN3A3 axis, decreasing CSC frequency and tumor growth ultimately." (PMID 36497444, 2022). "On the other hand, BTN3A3 expression was positively correlated with the density of CD8+T cells, anti-tumor immune response, and less invasive phenotype in non-small cell lung cancer (NSCLC) patients." (PMID 36362212, 2022). "At present, it has been confirmed that BTN3A1 can kill tumor cells by activating Vγ9Vδ2 T cells, which indicates that it is related to tumor immunity, but little is known about BTN3A2 and BTN3A3." (PMID 36059652, 2022). "Other immune-related genes of the nine-IRGP signature, including BTN3A3, RORC, and AGER, participate in promoting tumorigenesis, decreasing efficacy of immunotherapy, and preventing tumor immune killing through a variety of immunological mechanisms." (PMID 32211443, 2020). "Overexpression of both BTN3A3 and RPS3A increases cellular oxygen consumption rate (OCR) and reactive oxygen species (ROS) levels, which play a role in regulating the Mitogen-activated protein kinases (MAPKs) pathway and tumor cell growth." (PMID 39891297, 2025). "Moreover, we also identified BTN3A3, a surface molecule contributing to the recognition of phosphoantigens and DNAM-1 (CD226), an activating receptor recognizing CD155 and CD112 that are often upregulated on tumour cells." (PMID 39451262, 2024). "BTN3A3 is one of the B7-related butyrophilins (BTN) family members, contains extracellular IgV and IgC domains, a transmembrane domain, and an intracellular B30.2 domain that show some structural features of the B7 family as well as distributed in diverse types of tumor cells." (PMID 36497444, 2022).
cancer (6 papers, 2014 to 2025). A tumor composed of atypical neoplastic, often pleomorphic cells that invade other tissues. "Experiments on proliferation, migration and invasion have proved that inhibition of ERK1/2 activation can save cancer promotion caused by BTN3A3 knockdown." (PMID 36059652, 2022). "Finally, the cancer promotion phenomenon caused by BTN3A3 knockdown can be improved by using ERK1/2 inhibitor SCH772984." (PMID 36059652, 2022). "In line with our analysis, BTN3A3 antigen and its cognate autoantibody was recently suggested as a valuable target for further analysis as potential cancer biomarker." (PMID 25594006, 2014). "As far as BTN3A3 is concerned, studies have shown that it may play an important role in some types of cancer." (PMID 36059652, 2022). "Butyrophilin Subfamily 3 Member A3 (BTN3A3) is a type I transmembrane protein belonging to the immunoglobulin (Ig) superfamily, which is expressed in many cancers." (PMID 36059652, 2022).
infection (3 papers, 2020 to 2024). The state of being infected such as from the introduction of a foreign agent such as serum, vaccine, antigenic substance or organism. "The three ISGs with the most significant inhibitory effect, PFKFB3, BTN3A3, and CCDC92, decreased EBOV∆VP30 titers by nearly 1000-fold on day 6 post infection." (PMID 32528005, 2020). "Surprisingly, overexpression of BTN3A1 and BTN3A3 was found to restrict Mallard‐GFP rather than PR8‐GFP or maCal04‐GFP infection, implying that BTN3A3 specifically restricts avian IAVs." (PMID 38045831, 2023).
BTN3A3 also shares sentences with these, for which no sentence is quoted: ulcerative colitis (2 papers); Anxiety (1); Astrocytoma (1); bipolar disorder (1); hyperplasia of prostate (1); hypothyroidism (1); Inguinal hernia (1); rheumatoid arthritis (1); swine flu (1).